GNA14 (G protein subunit alpha 14)
Diseases named in the same sentence as GNA14 in open-access papers (continued):
Sharing a sentence is not in itself a finding about the gene and the disease.
tumor (12 papers, 2018 to 2025). "The diagnostic value of GNA14 as a predictor of HCC was evaluated in HCC tumor samples and compared with normal tissues." (PMID 33500727, 2021). "GNA14, encoding a Gα subunit of the G-protein complex, participates in GPCR signaling and has been linked to angiogenesis, vascular remodeling, and tumor progression in several cancers, including HCC." (PMID 41348762, 2025). "It is anticipated that the restoration of GNA14 expression or activity will enhance the immune infiltration of tumors and augment the capacity of the immune system to combat tumor growth." (PMID 39659788, 2024). "The potential mechanisms by which GNA14 affects tumor prognosis were preliminarily analyzed using bioinformatics analysis." (PMID 39659788, 2024). "This restoration can be achieved through gene therapy techniques, such as viral or nanoparticle-mediated delivery of GNA14, with the aim of re-establishing its expression within tumor tissues." (PMID 39659788, 2024). "Histological examination showed that Gna14 knockout mice suppressed malignant tumor progression due to decreased proliferation and increased apoptosis in polyps compared to controls." (PMID 37760541, 2023). "The GNA14 expression level was found to be higher in the adjacent tissues than in the tumor tissues, whereas GLS and MEX3B expression was lower in the adjacent normal tissues." (PMID 38304027, 2023). "And the expression of GNA14 is decreased in tumor tissues and is related to the poor OS of patients with HCC, indicating that it can be a tumor suppressor gene." (PMID 36463115, 2022). "To verify the expression of GNA14 in HCC, we initially used qRT-PCR to detect the mRNA expression of GNA14 in tumor tissues (n = 50) and matched adjacent normal tissues (n = 50) from the First Affiliated Hospital of Zhejiang University School of Medicine." (PMID 33500727, 2021). "The results revealed that the mRNA expression of GNA14 was downregulated in tumor tissues, and GNA14 mRNA expression was significantly negatively correlated with the methylation level of the DNA methylation sequencing region (R = -0.68, P = 0.008)." (PMID 33500727, 2021). "In 46 pairs (92%), the mRNA expression of GNA14 mRNA in tumor tissues was downregulated (7.2-fold) compared to that in matched normal tissues." (PMID 33500727, 2021). "Immunohistochemistry (IHC) revealed that GNA14 expression was decreased in the tumor tissues compared with the matched normal tissues." (PMID 33500727, 2021). "We found that three probes of GNA14 (ch9.991104F, cg12687527, and cg17301902) showed upregulation of methylation in tumor tissues compared to normal tissues." (PMID 33500727, 2021). "The invasion and migration ability of tumor cells overexpressing GNA14 were significantly inhibited in both in vitro and in vivo experiments." (PMID 33500727, 2021). "The immunohistochemical staining and western blot results of subcutaneous tumor tissues of nude mice also indicated that the expression of JMJD6 was significantly increased in the GNA14 overexpression group." (PMID 33500727, 2021). "Taken together, we reveal that GNA14/KLF7/HAS2 signaling cascade exerts tumor promoting function during UCEC development." (PMID 33892667, 2021). "According to the Oncomine database, GNA14 expression was downregulated in tumors and inversely related to tumor size and tumor grade." (PMID 33500727, 2021). "The IHC staining and western blot results of subcutaneous tumor tissues of nude mice also suggested that the expression of NICD1 was significantly increased in the GNA14 overexpression group." (PMID 33500727, 2021). "A higher level of GDP but not GTP was accompanied by downregulation of GPCR‐related genes (GNG11 and GNA14) in the tumours of both LUSC and LUAD." (PMID 31461552, 2019). "It is assumed the stimulation of the TNF-α/TNFR1 signaling in the tumor microenvironment enhances GC progression by inducing Noxo1 and GNA14." (PMID 29867530, 2018).
tumor (continued). "Strategies to restore GNA14 expression in NPC cells may have the potential to inhibit tumor growth and metastasis." (PMID 39659788, 2024). "It was found tumor tissues with low GNA14 expression represented lower immune and stromal scores." (PMID 39659788, 2024). "The function of GNA14 in tumor development may depend on the specific tumor type, with the protein exhibiting either tumor-promoting or tumor-suppressing properties." (PMID 39659788, 2024). "In conclusion, we found that GNA14 expression was down-regulated in NPC tissues, and its low expression may be closely associated with advanced tumor stage and distant metastasis." (PMID 39659788, 2024). "Mechanistically, GNA14 likely controls the retinoblastoma pathway by inducing Notch1 cleavage to stop tumor growth, and it may also prevent tumor cell migration by suppressing the expression of Jumonji domain-containing 6 (JMJD6)." (PMID 38304027, 2023). "The CCK8 assay showed that GNA14 could inhibit tumor cell proliferation in HCC by inducing G0 / G1 phase retardation in the HCC cell cycle." (PMID 33500727, 2021). "Several assays were performed to evaluate the effect of GNA14 on tumor metastasis." (PMID 33500727, 2021). "In the Wurmbach cohort, GNA14 expression was negatively correlated with tumor size and tumor grade." (PMID 33500727, 2021). "GNA14 regulated the RB pathway by promoting Notch1 cleavage to inhibit tumor proliferation, and might inhibit tumor metastasis by inhibiting the expression of JMJD6." (PMID 33500727, 2021). "As a potential tumor suppressor, whether GNA14 can inhibit the function of HCC is unknown." (PMID 33500727, 2021). "Immunohistochemistry (IHC) was used to detect the expression of GNA14 in tumor tissues of 165 NPC patients, and we analyzed the relationship between GNA14 expression and patient prognosis." (PMID 39659788, 2024). "Therefore, we speculated that GNA14 inhibited tumor invasion and migration by inhibiting JMJD6." (PMID 33500727, 2021). "It is worth noting that the expression of GNA14 was significantly negatively correlated with HBV infection, vascular invasion, tumor differentiation, and prognosis." (PMID 33500727, 2021). "The TNF-α/TNFR1 signaling could promote GC occurrence by inducing NADPH oxidase organizer 1 (Noxo1) and G protein subunit alpha 14 (GNA14), which are crucial in the tumorigenicity and stemness of GC cells, in tumor cells." (PMID 29867530, 2018). "Hence, the GNA14 protein in tumor tissues of patients with (n = 10) or without (n = 10) HBV infection was measured, which revealed that patients with HBV infection had lower GNA14 levels." (PMID 33500727, 2021). "Additionally, the HIF2α transcriptional targets EDN1, EPO, GNA14, and VEGFA were significantly upregulated in the tumor and might also promote tumor progression." (PMID 32235007, 2020). "HIF-2α target genes EDN1, EPO, GNA14, and VEGF were significantly upregulated in the tumor bed but not in the surrounding liver tissue." (PMID 32235007, 2020). "HIF-2α transcriptional targets EDN1, EPO, GNA14, and VEGFA were significantly upregulated in the tumor bed but not the surrounding liver tissue, indicating hyperactivation of the hypoxia signaling pathway within the tumor." (PMID 32235007, 2020).
cancer (9 papers, 2017 to 2025). A tumor composed of atypical neoplastic, often pleomorphic cells that invade other tissues. "Knocking out GNA14 in cells can significantly promote cancer growth, and the related mechanism is linked to the activation of signaling pathways such as MAPK/JNK, PI3K/AKT, and Notch1." (PMID 37405532, 2024). "Recent investigations have highlighted the role of Gαq subunits encoded by GNAQ, GNA11, GNA14, and GNA15 in cancer development." (PMID 37760541, 2023). "Krüppel-like factor 7 (KLF7) acts as an oncogene in various cancer types, whereas the connection between GNA14 and KLF7 in UCEC is unclear." (PMID 33892667, 2021). "TNF-α is able to promote the development of cancer through activating cancer-related pathways or up-regulating Noxo1 and Gna14." (PMID 28938560, 2017). "Some studies have shown that GNA14 can act as an oncogene to promote cancer development." (PMID 39659788, 2024). "However, the downstream cell signaling mechanisms by which GNA14 affects cancer cell proliferation are less well understood." (PMID 37760541, 2023). "Recent studies have shown that GNA14 may play a pivotal role in cancer development." (PMID 33892667, 2021). "These associations are likely related to the abnormal GNA15 expression in PDAC cancer cells, whereas GNAL, GNAO1, and GNA14 are preferentially expressed in normal pancreas, which is progressively lost as transformed tissue prevails." (PMID 34290274, 2021). "Collectively, these analyses show that GNA14 may accelerate CRC cell proliferation and malignant tumor progression through ERK and β-catenin pathways." (PMID 37760541, 2023).
GNA14 also shares sentences with these, for which no sentence is quoted: adenocarcinoma (1 paper); alopecia (1); atopic dermatitis (1); bladder urothelial carcinoma (1); cholangiocarcinoma (1); dengue (1); fibrosarcoma (1); glioma (1); head and neck squamous cell carcinoma (1); ichthyosis (1); lung carcinoma (1); lung squamous cell carcinoma (1); malignant vascular tumors (1); neuroblastoma (1); Obesity (1); oral squamous cell carcinoma (1); papillary thyroid carcinoma (1); Parkinsonism (1); Pruritus (1); uterine corpus endometrial carcinoma (1); vascular malformation (1).